IL10 (interleukin 10)
Diseases named in the same sentence as IL10 in open-access papers (continued):
Sharing a sentence is not in itself a finding about the gene and the disease.
tumor (continued). "In conclusion, IL-10 successfully recovers MHC class I expression and enhances tumor antigenicity in PTC with concomitant HT." (PMID 32348468, 2020). "On the one hand, MDSCs can produce high levels of immunosuppressive molecules, such as arginase 1 (ARG1), iNOS, TGFβ, IL-10, COX2, and indoleamine 2,3-dioxygenase (IDO), to immediately inhibit effector T cell-mediated cytotoxicity to tumor cells." (PMID 32551121, 2020). "We previously observed that JHD attenuated the expression of interleukin-10 (IL-10) and transforming growth factor beta (TGF-β) in tumor." (PMID 32140106, 2020). "Firstly, the Fas ligand is upregulated in response to tumor-derived VEGF, interleukin 10 (IL-10), and PGE3." (PMID 32983126, 2020). "Many of the suppressive machineries of MDSCs can be potentiated by tumor derived-exosomes, including expression of ARG1 and iNOS, and production of IL-10 and VEGF." (PMID 32793192, 2020). "Bregs suppress the immune responses against HCC primarily via the CD40/CD40L mediated production of IL-10 and TGF-β, which down-regulate TNF-α that is critical for halting tumor progression." (PMID 33230233, 2020). "An interaction between C3AR1 and IL10 has been shown previously in another type of immune cell; C3AR1 inhibited IL10 production by CD8+ tumor-infiltrating lymphocytes." (PMID 33176797, 2020). "TAMs are known to secrete anti-inflammatory cytokines such as IL-6, IL-10 and TGF-β, thereby enhancing immunosuppression in tumor microenvironment, leading to promotion of GBM cell growth and angiogenesis." (PMID 32765498, 2020). "In this study, we compared the effects of low-dose CTX at different time points on the expression of the anti-inflammatory cytokines IL-10 and TGF-β1, T-cell subsets including CD4+CD25+Foxp3+ T cells, and tumor immunity in mice." (PMID 32104586, 2020). "IL-6 and IL-10 were detected in HNSCC cell lines, primary HNSCC cells, as well as tumor-infiltrating immune cells." (PMID 33042814, 2020). "In tumor cells, hyperactivated STAT3 promotes the expression of immunosuppressive factors such as VEGF, IL-6, and IL-10." (PMID 32972405, 2020). "TAM-derived IL-10 and interactions with MDSCs result in decreased IL-6, IL-12, and MHCII, and increased anti-inflammatory IL-10, TGF-β1, and Foxp3+ Treg frequencies to facilitate tumor growth and immune tolerance." (PMID 33718121, 2020). "In contrast, M2 macrophages express immunosuppressive cytokines and growth factors like IL-10, Arg-1, CD206, VEGF, and EGF, and can thereby promote tumor proliferation, metastasis, and angiogenesis." (PMID 32850356, 2020). "If PD-1 blockade might induce IL-10 secretion by innate immune cells, as described in the previous section, and a parallel upregulation of IL-10R on T cells, these two combined events might cause severe dampening of CD8+ T cell antitumor activity, favoring tumor growth." (PMID 33168050, 2020). "Endostar combined with radiotherapy can inhibit tumor growth and downregulate the expression levels of TGF-β1 and IL-10 through synergistic action." (PMID 32669133, 2020). "M2 macrophages express arginase-1, Interleukin 10 (IL10) and TGF-β1, which reduce the anti-tumor activity of T cells." (PMID 32570988, 2020). "Both tumor‐infiltrating neutrophils and monocytes expressed Arginase 2, CD39 and CD73, IL10, iNOS, and Ptgs2 at increased levels compared to circulating cells." (PMID 31793740, 2020). "M2-like TAMs secrete strongly immunosuppressive cytokines such as IL-10, TGF-β, arginase-1 (Arg1), and prostaglandins to inhibit the activity, proliferation and antitumorigenic effects of T-cells in the tumor microenvironment." (PMID 32326073, 2020). "Tumor-derived TLR2 ligands were shown to be critical for the generation of immunosuppressive IL-6- and IL-10-producing DCs." (PMID 32486257, 2020). "Coculture systems containing IL-10-pretreated PTC cells and CD3+CD8+CD25+ T cells were employed to further examine the possible impact of IL-10 on tumor immunity." (PMID 32348468, 2020).
tumor (continued). "In the same groups, the highest increase in IL-10 was observed, which is important for the normal function of helper CD4+ lymphocytes, CD4+ lymphocyte-mediated immune response, and suppression of tumor-mediated inflammation." (PMID 33126765, 2020). "Lag-3+ Tregs produces high amounts of IL-10 and transforming growth factor beta (TGF-β) and expand in tumor tissue of patients with melanoma and colorectal cancer." (PMID 33101304, 2020). "CDDO-Me-mediated reductions in myeloid tumor cell numbers are likely attributable to significantly attenuated expression of CCL2, IL-10, and VEGF, which also regulate monocyte recruitment to TAMs37." (PMID 32300202, 2020). "When CD14+ monocytes engulf tumor-derived miR-21-containing exosomes, they display increased expression of M2-like markers (CD206, CD163, IL-10) and down-regulation of M1-like markers (IL-18, IL-12B, HLA-DR)." (PMID 32486098, 2020). "IL-10 is secreted in the TME and it has been shown to induce an exhausted phenotype on tumor infiltrating T cells characterized by low proliferation and suppressed secretion of cytokines associated with an effector phenotype as IL-2, IFNγ and TNFα." (PMID 32937953, 2020). "The pro-tumor markers TGFβ and VEGF were more strongly expressed by GAMs in DAs than in OGs, while IL10, PD-L1, CD206, and IDO were similarly expressed by GAMs in DA and OGs." (PMID 32117733, 2020). "On the contrary, M2-like macrophages contribute to tumor progression by enriching anti-inflammatory cytokines in tumor TME, such as IL-10 and TGF-β, which typically promote immunosuppression, cancer cell proliferation, invasion, and metastasis." (PMID 32184777, 2020). "Widespread cell death in breast cancer during postpartum involution triggers wound-healing cytokines, including IL-4, IL-13, and IL-10, in the TME to promote metastatic tumor progression." (PMID 32346605, 2020). "The HBV infection–related HCC immunosuppressed tumor microenvironment features upregulation of PD-1 in CD8+ T cells; long-lasting inhibition of Tregs via higher levels of IL-10 and TGF-β secretion; and the co-inhibitory signal of LAG3, TIM-3, and CTLA-4." (PMID 32547550, 2020). "Recent reports indicate IL-10 is capable of stimulating the proliferation and activity of CD8+ T cells in the TME, responses that promote anti-tumor immunity." (PMID 31947933, 2020). "Tumor cells consistently release multiple immunosuppressive factors, including vascular endothelial growth factor (VEGF), TGF-β, IL-10, and PGE-2, to facilitate tumor growth and immune escape." (PMID 32754587, 2020). "IL-10 and TGF-β have been demonstrated to be involved in the suppression of the anti-tumor immune response of Treg cells." (PMID 32872659, 2020). "In addition, we recently demonstrated a strong association of IL-10 secreted by regulatory T cells with patients’ survival not only in the tumor tissue but also in the unaltered mucosa close to the resection margin representing a local immunological field effect." (PMID 32298379, 2020). "MDSCs rely on fatty acid-β oxidation (FAO) to fuel the synthesis of inhibitory cytokines (i.e., IL-10, TGF-β), which are generally required to both restrain T lymphocytes anti-tumor response and sustain tumor cell aggressiveness thus favoring metastases." (PMID 32133298, 2020). "Depending upon the TME, TAMs are either transformed to inflammatory TAMs which suppress tumor growth by producing cytokines such as IL-12 and TNF or become anti-inflammatory to support tumor growth by producing TGF-beta, IL-10, and arginase." (PMID 33281826, 2020). "The TME contains higher levels of immune regulatory factors, such as IL-10, RA, and TGF-β that actively suppress differentiation and expansion of tumor-specific effector T cells." (PMID 32132993, 2020). "For example, tumor-infiltrating MDSCs stimulated with TGF-β and IL-10 demonstrated high ARG1 activity." (PMID 32499785, 2020). "In addition, IL10 might promote tumor cell proliferation and metastasis through immunosuppression." (PMID 32012488, 2020).
tumor (continued). "Treatment with pegylated IL10 restores tumor-specific CD8 T-cell accumulation and controls tumor growth in mice." (PMID 33381115, 2020). "IL-6 released by TAMs induces the production of IL-10 by tumor cell via SATA3 signaling, which further enhances the IL-10 level within TME facilitating Tregs activation, survival, and accumulation." (PMID 32508809, 2020). "Culture media from single tumor cells during 24-h incubation were used to estimate the levels of the cytokines IFN-γ, IL-10, and TFG-β." (PMID 32733437, 2020). "G-CSFR−/− macrophages demonstrated increased NOS2 expression and tumor killing ability, while the addition of G-CSF to wildtype (WT) macrophages led to decreased NOS2 activity and increased IL-10 production to promote a pro-tumorigenic phenotype." (PMID 33036138, 2020). "Tumor-associated Macrophages (TAMs) secrete immunosuppressive cytokines TGF-B, IL-6, IL-10 that result in downregulation of costimulatory molecules and MHC expression lead to reduced phagocytic activity and reduced anti-tumor immunity." (PMID 33281826, 2020). "IL-10 derived by TAM also supresses MHC class II expression on monocytes and down-regulates the production of IFN-γ and TNF-α in GBM, thus preventing anti-tumor activity." (PMID 32765498, 2020). "Another transcription factor, Foxp3, promotes tumor growth by suppressing IL-10- and/or TGF-β-mediated tumor cell killing after increased infiltration of Treg cells." (PMID 32775468, 2020). "Tumor cell products (such as IL-10, IL-4, and CCL2) affect the M1/M2 transformation of TAMs, and TAMs, in turn, regulate the biological behavior of tumor cells by secreting small molecular substances." (PMID 32653013, 2020). "The gene expression of IL10, TGFbeta1, S100A8, S100A9, and IL10RA was upregulated in TAMs compared to tumor cells isolated from the ascites of OC patients." (PMID 33194645, 2020). "Elevated IL-10 expression in PTC with concomitant HT restores MHC class I expression and interferes with tumor immunity." (PMID 32348468, 2020). "An important finding of this study is that selective inhibition of PI3Kβ and -δ isoforms reduced IL-10 and TGFβ expression in toll-like receptor (TLR)-activated DCs pulsed with dead tumor cells in vitro." (PMID 33552053, 2020). "In vivo, tumor volume and weight were reduced, and the expression of VEGF, EGF, IL-10, TGF-β, and CD34 was suppressed in the tumor microenvironment, while cell apoptosis was induced." (PMID 32595723, 2020). "These exosomes significantly increased M2 macrophage-related cytokines such as IL10 and transforming growth factor-beta 2 (TGFB2), and modulate macrophages to a tumor-promoting M2 phenotype." (PMID 33363016, 2020). "Significantly, the key signature cytokine IL-10, known to be produced by all M2 macrophage phenotypes, was nearly four-fold higher in the NF2-negative tumours." (PMID 32070062, 2020). "Tumor-derived macrophages are also recruited to the TME, and can suppress immune cells via secretion of TGF-β and IL-10." (PMID 32153582, 2020). "Compared with pre-infusion tumor tissues, post-CAR-T cell infusion tumor specimens show markedly upregulated expression of many immunosuppressive molecules, particularly IDO1 and Foxp3, and in some cases, IL-10, PD-L1, and/or TGF-β." (PMID 32117960, 2020). "NO is reported to regulate the expression of various cytokines, growth factors and chemokines, including IL-6, IL-10, IFNγ, TGFβ, M-CSF, VEGF and MCP-1, which are important in tumor growth and metastasis." (PMID 32509271, 2020). "MDSCs can promote the survival and angiogenesis of tumor cells and inhibit the function of T cells by producing the immunosuppressive molecules TGF-β, IL-10, Arg1, and iNOS." (PMID 32823603, 2020). "The function of IL10-producing CD1dhigh CD5+ B cells, that suppress anti-tumor immunity by stimulating the development of Tregs and suppressing CD8+ T-cells is best described." (PMID 32582698, 2020).
tumor (continued). "Tumor cytokines’ dynamics indicate that as the tumor grows, HMGB1, IFN-γ and μ1 (IL-6, IL-17, IL-21, IL-22) increase in density, but TGF-β and μ2 (IL-10, CCL20) stay relatively constant." (PMID 33291412, 2020). "We show that the treatment of NSCLC spheroids with Peptide R, besides preventing tumor cell dissemination, decreases expression of immunosuppressive molecules, such as CD73, CD38, and IL-10." (PMID 33123122, 2020). "Some immune cell types have immunosuppressive properties and can facilitate tumor growth—for example, FOXP3+ regulatory T cells and interleukin-10-secreting B cells." (PMID 33276550, 2020). "Endostar combined with radiotherapy can inhibit the tumor growth and downregulate the expression levels of TGF-β1 and IL-10 through a synergistic action, providing further reference for later clinical experiments." (PMID 32669133, 2020). "Tumor-derived CSF-1 recruits macrophages into the TME, resulting in increased IL-10 levels and defective anti-tumor CD8+ T cell responses." (PMID 32121071, 2020). "Studies have found that TAMs can produce not only immunosuppressive cytokines (IL-10 and transforming growth factor-β (TGF-β)), but also chemokines such as CCL5, CCL20, and CCL22 that recruit regulatory T cells into tumor tissues." (PMID 33363016, 2020). "A tumor-promoting role of COX-2 has been demonstrated in tumor-bearing mice studies, where deletion or selective inhibition of COX-2 decreased secretion of IL-10 and increased production of IL-12 and IFN-γ." (PMID 32384638, 2020). "Such accumulation of adenosine within the intratumoral milieu induces a persistent secretion of immunosuppressive cytokines, such as IL-10 and TGF-β, contributing to tumor immune evasion." (PMID 32708507, 2020). "Taken together, our data imply that IL-10-mediated signaling via STAT3 elicits immunosuppressive responses in CD103+ cDC1s, thereby reducing CD103+ cDC1-mediated anti-tumor immunity." (PMID 31947933, 2020). "These cells produce various tumor-promoting cytokines, including TNF-α, IL10, and IL17A, and also the less well-studied cytokines such as IL21 and IL26." (PMID 31948053, 2020). "TAMs secrete inflammatory cytokines and factors such as interleukin 6 (IL-6), interleukin 10 (IL-10), and TGF-β in the tumor microenvironment, which facilitate the inflammatory microenvironment to promote cancer progression and metastasis." (PMID 32326073, 2020). "We further detected IL10 expression in PBS or bevacizumab-treated tumors and surprisingly found IL10 was highly expressed in bevacizumab-treated tumor." (PMID 33214550, 2020). "MDSCs induce the development of Tregs in vitro and in tumour-bearing mice and that Tregs induction was dependent on MDSC-secreted IL-10 and IFN-γ." (PMID 32680511, 2020). "Specifically, tumor tissue supernatants from WT and GCSFR−/− mice tumors were assessed for the production of IFNγ, IL-10, IL-17A, and IL-4, which are considered general markers of Th1, Tregs, Th17, and Th2 cells, respectively." (PMID 33042110, 2020). "TAMs are derived from monocytes attracted in the tumor microenvironment (TME) (via CCL2, CCL8) and are differentiated trough IL-4, IL-10, IL-13 and TNF-α stimuli." (PMID 32344813, 2020). "Factors secreted byTh2 such asIL-4, IL-10, and TGF-β play suppressive roles in tumor immune microenvironment, and promote tumor recurrence and metastasis." (PMID 32372963, 2020). "The cells of tumor and TME secrete CCL2 and macrophage colony-stimulating factor (M-CSF) and attract a large number of inflammatory monocytes to tumor sites where they differentiate into TAMs due to secretion of IL4, IL10, and IL13." (PMID 32582698, 2020). "The tDCs can be induced by products of pathogens, VEGF, tumor-released cytokines (e.g., TGF-β and IL-10), and IL-10-secreting Tregs." (PMID 32499786, 2020). "IL-10 has an immunosuppressive function, and TGF-β directly inhibits activation of CD8+ cytotoxic T lymphocytes, significantly reducing the effect of tumor immunity." (PMID 32218692, 2020).
tumor (continued). "The anti-tumour positive immunomodulatory change is more discerned in terms of Tregs, CD8+ T cells, TGF-β, IFNγ, IL-10 and IL-17 respectively." (PMID 32466214, 2020). "Cytokines, like IL-10, IL4, IL-6, and TGF-β, released by these cells can inhibit both innate and adaptive immunity and can also directly promote tumor progression." (PMID 32595757, 2020). "In corresponding tumor-bearing mice, these PD-1hi Bregs mediated the reduction and dysfunction of CD8+ T cells after triggering PD-1 in an IL-10-dependent manner." (PMID 33193391, 2020). "In supernatants from tumour cell killing assays, we found a similar immune mediator profile (TNFα, MCP-1, IL-10, CXCL-10, IL-1β, IL-6, and IL-23) to that previously detected with IgE cross-linking on the surface of monocytes." (PMID 33203088, 2020). "We found that these receptors are highly correlated to the innate and adaptive immunity-related cells, as well as IL-10, IL-6, CXCL10, CCL2-CCL5, TGFB1 in KIRC tumors, whereas in KIPRP tumor tissues IL8, IL1A, and TNF were highly correlated." (PMID 33330620, 2020). "Combination with anti–CTLA-4 led to tumor regression accompanied by enhanced T cell activity, increase in activated CD86+ monocytes in the tumor, augmentation of pro-inflammatory IFNγ, TNFα, and IL-6 and decrease in immunosuppressive MCP-1 and IL-10 cytokines." (PMID 32793228, 2020). "MDSCs expressing anti-inflammatory factors such as interleukin (IL)-10 and transforming growth factor-beta (TGFβ) play important immunosuppressive roles in the TME to promote tumor development and expansion." (PMID 32942545, 2020). "The aim of this study was to evaluate the role of IL-10 in patients with PTC with concomitant HT, analyzing its potential function from the view of tumor immunity through in vitro experiments." (PMID 32348468, 2020). "As a consequence, TAMs produce IL‐10, TGF‐β and matrix metalloproteinases (MMPs) to enhance tumour growth and progression." (PMID 33169503, 2020). "In CCA, tumor cells are a reservoir of protumorigenic and immunosuppressive molecules, such as IDO, IL-10, and TGF-β, which participate in the immunosuppression of the effector CTL and the attraction of innate immune cells as TAN, TAM, MDSC, and Treg." (PMID 32781527, 2020). "This DC phenotype is driven by tumour secretion of VEGF-A, TGFβ, and IL-10, and aided by hypoxia and lactic acid production in the TME." (PMID 32937961, 2020). "In a syngeneic model of OVA-expressing EL4 tumors (lymphoma), IL-10-producing γδ T cells suppress the CD8-dependent anti-tumor response, and their depletion significantly reduces tumor growth." (PMID 33042132, 2020). "Using a B-cell knockout mice model, Inoue and colleagues demonstrated that EL-4 gag tumor cells stimulated B cells to secrete IL-10, which in turn inhibited IFN-γ production and tumor elimination by NK cells." (PMID 33193391, 2020). "The adenosine-AR signals in dendritic cells upregulate IL-10, IDO-1, TGFβ, and arginase-2, thus facilitating naïve T-cell differentiation toward Th2 lineages and promoting tumor growth." (PMID 32775303, 2020). "In another study, Ang-2 also increased expression of interleukin-10 (IL-10), mannose receptor (MRC-1), and chemokine (C-C motif) ligand 17 (CCL-17) in TEMs, which are three markers for the so-called “pro-tumor M2-like macrophages." (PMID 32085414, 2020). "To further support the notion that the CD163-labelled M2 macrophages were activated, we showed expression of IL-10, TNF-α, TGF-β1 and IL-6 in all tumour tissues." (PMID 32070062, 2020). "Numbers of CD96+ NK cells were increased in tumor sites in HCC and exhibited functional exhaustion with decreased of IFN-γ and TNF-α production, low perforin and granzyme B levels, and high IL-10 and TGF-β expression." (PMID 32714324, 2020). "On the other hand, MDSCs can also promote tumor angiogenesis and epithelial-mesenchymal transition (EMT) by secreting molecules such as vascular endothelial growth factor (VEGF), TGFβ, and IL10." (PMID 32551121, 2020).